RSPO3 (R-spondin 3)
Diseases named in the same sentence as RSPO3 in open-access papers (continued):
Sharing a sentence is not in itself a finding about the gene and the disease.
infection (6 papers, 2016 to 2023). The state of being infected such as from the introduction of a foreign agent such as serum, vaccine, antigenic substance or organism. "Our data indicate that loss of Bmp2 upon infection drives the increased expression of Rspo3, which expands from the stroma around the base to that higher up along the gland axis." (PMID 35332152, 2022). "In addition, we find that BMP2 inhibits Rspo3 expression in stromal cells, indicating that the loss of Bmp2 expression upon infection is responsible for the increased expression of Rspo3." (PMID 35332152, 2022). "In the corpus, on the other hand, exploiting R-spondin 3 knockout and knock-in mouse models, R-spondin 3 was shown to be important not only for boosting Wnt signaling but also for the activation of YAP signaling in the gland base upon infection with H. pylori." (PMID 37152042, 2023). "As expected, immunofluorescence labeling revealed that, upon infection of Rspo3-WT mice with H. pylori, the GIF+ compartment was reduced and the GIF+GSII+ cell compartment was enlarged." (PMID 36099044, 2022). "In contrast, Rspo3 expression was downregulated 2-fold by day 3 of infection while Rspo1 was downregulated 2-fold by day 6 of infection." (PMID 27046199, 2016). "We confirmed that infection with H. pylori induces a shift of predominantly membrane-associated to predominantly nuclear YAP and that the active form of the protein is also more abundant in infected Rspo3-KI mice compared with infected WT mice." (PMID 36099044, 2022). "In contrast, we observed massive hyperproliferation in Rspo3-KI mice upon infection." (PMID 36099044, 2022). "To determine if the downregulation of Rspo1 and Rspo3 was potentially a compensatory response to the increase in Rspo2 during infection, we assessed R-spondin levels in resistant C3Ou.B6-Cri1 congenic mice at days 3, 6, and 9 post-infection." (PMID 27046199, 2016). "Thus, in addition to an absolute increase in RSPO3 expression, further changes in niche signaling may affect the responsiveness of cells in the context of infection and epithelial injury." (PMID 36099044, 2022). "We have recently reported that in the antrum, in addition to RSPO3, BMP signaling also forms a gradient along the base-lumen axis and affects epithelial differentiation and that BMP signaling was altered upon infection with H. pylori." (PMID 36099044, 2022). "In summary, we find that RSPO3 induces YAP expression in gland cells and that infection with H. pylori promotes activation of the YAP signaling pathway." (PMID 36099044, 2022). "The number of parietal cells was significantly affected neither by a reduction of Rspo3 expression nor by infection of Rspo3-WT mice with H. pylori or a combination of Rspo3-KO and H. pylori infection." (PMID 36099044, 2022). "Again, the number of parietal cells was not affected by infection with H. pylori, but their number was increased in Rspo3-overexpressing mice compared with controls." (PMID 36099044, 2022). "Infection of Rspo3-KO mice led neither to a further reduction of the GIF compartment nor to a further increase of GIF+GSII+ cells per gland in Rspo3-KO mice." (PMID 36099044, 2022). "Importantly, the stronger response to infection by Rspo3-overexpressing mice compared with WT mice was not driven by higher bacterial counts or an additional upregulation of Rspo3 upon infection." (PMID 36099044, 2022).
adenocarcinoma (3 papers, 2016 to 2022). A common cancer characterized by the presence of malignant glandular cells. "The upregulated expression of RSPO3, ADAMTS8 and DOCK8 was associated with the overall survival (all P < 0.05) and disease-free survival of adenocarcinoma patients (all P < 0.05), which indicated that RSPO3, ADAMTS8 and DOCK8 might influence the prognosis of adenocarcinoma." (PMID 27980454, 2016).
renal diseases (1 paper, 2020). "Interestingly, the RSPO3 locus has been identified in two studies to be linked with renal diseases including abnormal blood urea nitrogen (BUN), a hallmark for glomerular filtration dysfunction." (PMID 32324134, 2020).
RSPO3 also shares sentences with these, for which no sentence is quoted: breast carcinoma (5 papers); bladder cancer (4); Abdominal obesity (2); acute lymphocytic leukemia (2); esophageal cancer (2); fatty liver (2); metabolic disease (2); acute GVHD (1); alcoholic hepatitis (1); Alzheimer disease (1); amyloid (1); Arrhythmia (1); basal cell carcinoma (1); brain cancer (1); brain disorder (1); colorectal (1); cyst (1); endothelial dysfunction (1); gastric diseases (1); glioblastoma (1); inflammatory bowel disease (1); invasive breast carcinoma (1); liver cancer (1); mammary adenocarcinomas (1); metabolic syndrome (1); nonalcoholic steatohepatitis (1); osteoarthritis (1); osteosarcoma (1); pheochromocytoma (1); Primary hyperaldosteronism (1).
A further 4 diseases each share a sentence with RSPO3 in 1 paper.